CXCL11 (C-X-C motif chemokine ligand 11)
Diseases named in the same sentence as CXCL11 in open-access papers (continued):
Sharing a sentence is not in itself a finding about the gene and the disease.
tumor (continued). "The relative overexpression of IL13RA2 and underexpression of CXCL11 and IFNA7 also imply tumor-related chronic inflammatory suppressive TME which would support immune evasion." (PMID 41511314, 2025). "CXCL11, a protective biomarker, promotes M1 macrophage polarization via JAK2/STAT1, supporting the anti-tumor role of M1 TAMs in OC." (PMID 41280929, 2025). "This trend was similarly observed at the protein level, as Western blot results indicated significant upregulation of CXCL10, CXCL11, OAS2, MTIE, and MTIX in tumor tissues, although FAT1 exhibited an opposite trend compared to the qPCR results." (PMID 40574841, 2025). "The interaction between chemokines such as CXCL9, CXCL10, CXCL11, and their receptor CXCR3 is known to affect immune cell behavior, potentially enhancing tumor growth and spread." (PMID 39964621, 2025). "The ligands CXCL9, CXCL10, and CXCL11 all bind to CXCR3 and are primarily secreted by immune cells such as leukocytes and macrophages, as well as by dendritic cells, fibroblasts, and tumor cells." (PMID 40362215, 2025). "qRT-PCR revealed significant upregulation of CXCL10, CXCL11, ME1, MT1X, FAT1, OAS2, and MT2A in tumor tissues compared to normal tissues." (PMID 40574841, 2025). "In a mouse LLC tumor model, intravenous injection of such NP significantly reduced tumor volume and increased CXCL9, CXCL10, and CXCL11 protein levels in tumor tissues." (PMID 40124344, 2025). "Based on this evidence, we select CXCL10, CXCL11, and IFNG as rational proof-of-concept candidates for proposing a gene-therapeutic approach that remodels the TME by inducing tumour-intrinsic expression of immunostimulatory cytokines." (PMID 41366257, 2025). "Chemokines such as CXCL4, CXCL9, CXCL10, CXCL11, CXCL13, and CCL5 contribute to the accumulation of CD8+ T cells and B lymphocytes in tumor tissues and inhibit angiogenesis." (PMID 41223031, 2025). "Like CXCL10 and CXCL11, CCL3 and CCL4 have been attributed both tumor-promoting and anti-tumor effects." (PMID 40895532, 2025). "CXCL9, -10, -11 are CXCR3 ligands, expressed by several different cells within a tumor, that recruit T-cells and NK cells, with CXCL9 and 10 primarily recruiting activated CD4+ and CD8+ effector cells and CXCL11 recruiting or promoting development of T-regs." (PMID 40176808, 2025). "This inhibition promotes the secretion of immune-modulatory factors CXCL10, CXCL11, EBI3, and FLT3LG by tumor cells, thereby alleviating immunosuppression and enhancing CD8+ T cell recruitment into the tumor microenvironment and boosting antitumor immunity." (PMID 41293150, 2025). "A recent elegant study showed that immune evasion in ARID1A mutant tumours is mediated by impaired chromatin accessibility of IFNγ responsive genes, including Th1 chemokines CXCL9, CXCL10 and CXCL11." (PMID 39920335, 2025). "On The other hand, we identified a complex interplay involving CD36, CXCL11, GZMB, MT2 A, and CD8 + T cells that regulates immune function and tumor cell cycle processes." (PMID 40382758, 2025). "In tumor regions, the expression levels of CCL2, CCL5, CCL20, CXCL9, CXCL10, CXCL11 and CXCL12 were generally higher in hot tumors than in the other two groups." (PMID 37847338, 2024). "Initially TNF-γ works by recruiting cohorts (CXCL9, CXCL10, CXCL11, and CXCR3) to promote antigen presentation (MHC class I and class II), T-cell initiation and activation (CD80, CD86, and CD40), and tumor cell killing (Fas and FASL)." (PMID 39835116, 2024). "The chemokines CXCL9, CXCL10, and CXCL11 are generally produced by activated macrophages and dendritic cells to facilitate CD8+ T cell infiltration to injured or tumor tissues." (PMID 39324134, 2024). "For CD8+ T cells to effectively infiltrate the tumor site, chemokine receptors, such as CXCR3, must interact with their corresponding chemokines (CXCL9, CXCL10 and CXCL11)." (PMID 39409972, 2024).
tumor (continued). "Cxcr3, a chemokine receptor with anti-tumor effects expressed in effector CD8+ T cells, Th1 cells, and NK cells, interacts with its ligands Cxcl9, Cxcl10, and Cxcl11, promoting immune cell recruitment to TME." (PMID 38622609, 2024). "In cancer cells, the binding of CXCL11 to CXCR3 enhances EMT and cancer stemness, promoting tumor progression." (PMID 39543650, 2024). "The CXCL9, CXCL10 and CXCL11/CXCR3 axes have been demonstrated to regulate immune cell migration, differentiation, and activation, leading to tumour suppression." (PMID 39233332, 2024). "These core genes contained at least 8 (PPP2R2A, CXCL10, CXCL11, GBP1, IRF1, RARRES3, STAT1, and TAP1) previously identified regulators of tumor progression and distant metastasis." (PMID 38545852, 2024). "On the opposite side, VEGF-A suppresses pro-inflammatory T-cell infiltration into the tumor through inhibition of NF-κB and TNF-α-induced downregulation of CXCL10 and CXCL11." (PMID 38726320, 2024). "Activation of the CXCL11/CXCR3-axis in CD8+ T cells significantly increased apoptosis of cancer cells and reduced tumor growth both in in vitro and in vivo." (PMID 39543650, 2024). "Following YY001 treatment, the tumor tissue exhibited increased secretion of cytokines such as CXCL9, CXCL10, and CXCL11, which contribute to the recruitment of more T cells." (PMID 38560505, 2024). "Docetaxel can potentially enhance anti-tumor efficacy by increasing the secretion of HMGB1 and CXCL11, consequently promoting the recruitment of CD8+ T cells into the tumor microenvironment." (PMID 38850524, 2024). "Some of the upregulated genes such as CXCL13 and CXCL11 and KLK5 have been experimentally verified in prior studies to regulate humoral immune response and support tumor infiltration." (PMID 37697300, 2023). "Major initiators of tumor inflammation such as CCL2, CXCL1, CXCL2, CXCL11, CSF1, LTB, and TNFSF10 were found to increase in both cell lines, while inflammation suppressors like IL13and IL1RN were decreased." (PMID 36831395, 2023). "CXCL9, CXCL10, and CXCL11 are ligands of CXCR3 and have been increasingly recognized as key regulators of the tumor microenvironment." (PMID 37686653, 2023). "We made similar observations for Stat1 and other STAT1 target genes including Irf1, Cxcl10, and Cxcl11, which suggested that PARP14 was induced specifically in IFNγ-inflamed tumours but independently of α-PD-1." (PMID 37752135, 2023). "In fact, RT sustains CD8 T-cell recruitment into the tumor by inducing the expression of several factors, including IFNα, CXCL9, CXCL10, and CXCL11, as well as promoting extravasation by upregulating ICAM-1 and E-selectin on endothelial cells." (PMID 36831435, 2023). "NLRC3 showed moderate and strong correlations with CCL5, CXCL9, CXCL10, CXCL11, CXCR3, and CCR5, resulting in an increased recruitment of NK cells, TH1 cells, and CD8+ T cells in tumor tissues." (PMID 36808166, 2023). "Natural killer (NK) cells and Th1 cells share CXCR3 receptors and exert anti-tumor effects in response to stimulation by the specific ligands CXCL9, CXCL10, and CXCL11." (PMID 37063892, 2023). "The first study of note is an attempt by Liu and colleagues who noted KRAS-G12D mutation responsible for suppressing the PD-L1 targeted therapy and CXCL10/CXCL11 (chemokines) secretion, together suppressing the CD8+ tumor infiltrating lymphocytes (TILs)." (PMID 37970206, 2023). "CXCL11 is enriched in metastatic HCC tissues, and its knockdown in CAFs weakens tumor migration in coculture and orthotopic models." (PMID 36708970, 2023). "Chemo-taxis of effector T cells to the tumor depends on the expression of CXCR3 on T cells and the presence of its ligands, CXCL9, CXCL10, and CXCL11 within the TIME." (PMID 37377970, 2023). "Chemokine CXCL11 levels were greatly increased, resulting in enhanced CAR-T cell infiltration within the tumor microenvironment and greater recruitment of immune cells." (PMID 37513708, 2023).
tumor (continued). "Treg cells are mainly recruited to the tumor microenvironment by chemokines such as CCL1, CCL17, CCL22, CCL28, CXCL9, CXCL10, and CXCL11." (PMID 37686093, 2023). "B1R also regulated the production of the protumorigenic cytokines and chemokines IL-6, IL-8, CXCL11, and CCL5 in GBM, which contributed to tumor progression." (PMID 37627528, 2023). "CXCL9, CXCL10, and CXCL11 were expressed most prominently by cluster 11, which was annotated as CD14(+) monocytes derived from neoplasms." (PMID 37686653, 2023). "M1 macrophages exhibit enhanced antigen-presenting activity while secreting CXCR3 ligands (CXCL9, CXCL10, CXCL11) and CXCL16 to recruit Th1 and NK cells and secrete TNF-α, synergistically exerting anti-tumor functions." (PMID 37063892, 2023). "CXCL9, CXCL10, and CXCL11/CXCR3 are anti-tumor angiogenic factors, and the inhibition of tumor angiogenesis can be achieved via upregulating the expression of CXCL9, CXCL10, and CXCL11." (PMID 35770088, 2022). "The expression of cytokines, such as CXCL9, CXCL10, CXCL11 and CXCL13, that attract specific immune cells at the tumor site was significantly higher in HBV and HCV tumors than in non-B, non-C tumors." (PMID 36557005, 2022). "Our data indicate that a LINC00152/miR-205-5p/CXCL11 axis in HCC CAFs can affect the proliferative and migrative abilities of HCC cells in vitro and HCC tumor growth in vivo." (PMID 36435866, 2022). "CXCL11 can also bind to the CXCR3 receptor and mediate endothelial cell inhibition and hence tumor angiogenesis." (PMID 36354566, 2022). "In terms of liver metastasis, the interferon-α response gene set was enriched in a tumor burden of ≥1 cm3, and CXCL10, CXCL11 and SAMD 9 were highly expressed in the exosomal RNA which was validated using GSEA." (PMID 36230645, 2022). "We then focused on three genes (CD70, CXCL11, and HGF) which negatively correlated with favorable outcomes to further validate the key factor involved in tumor immune infiltration, especially the correlation with macrophages was mainly focused on." (PMID 35568859, 2022). "It is already known that CXCR3 is primarily expressed on vascular cells, NK cells, tumor cells, and activated T lymphocytes and binds to CXCL9 to CXCL11." (PMID 35978426, 2022). "A protein array on a lysate of tumors treated with MTX alone displayed a more than 1.5 fold increase of CCL17, CXCL11, CD160 and CXCL10, as compared to control tumor lysate." (PMID 36397148, 2022). "CXCL11 (also known as I-TAC) belongs to the chemokine superfamily and is expressed at a high level in different solid tumors, promoting tumor growth, metastasis, and lymphocyte infiltration." (PMID 36478746, 2022). "To exclude that analysis is biased by chemokine-induced cell proliferation, we maintained the various tumor cells with CXCL12, CXCL11 or both for 48 h and determined numbers of proliferating cells by BrdU-labeling." (PMID 36539774, 2022). "We demonstrate the existence of complex interplay between the CXCL11- and CXCL12-chemokine systems, which differs with respect to tumor cell type and cellular function." (PMID 36539774, 2022). "Exosomal mRNA analysis showed that CXCL10, CXCL11 and SAMD9 were highly expressed in CRC patients with liver metastasis, which was validated by tumor RNA sequencing using GSEA." (PMID 36230645, 2022). "There was a significant relationship with tumor stage in the group of CXCL2, CXCL10 and CXCL11 (P < 0.05)." (PMID 35181719, 2022). "For ADAMTS12, AEBP1, COL10A1, COL11A1, CXCL11, EPPK1, and WNT7B, their expression values were higher in tumor samples than in normal samples." (PMID 35505821, 2022). "Tumour-derived chemokines such as CXCL9, CXCL10, and CXCL11 are attracted by CXCR3 (expressed on activated CD8+ T cells), leading to their recruitment and development of anti-tumour immune response." (PMID 35406451, 2022).
tumor (continued). "In the TME, M1-like macrophages are capable of recruiting and activating CD8+ T cells and NK cells via antigen presentation to the T-cell receptor and the secretion of tumor-derived chemokines including CXCL9, CXCL10, and CXCL11." (PMID 36561315, 2022). "Among the chemokines known to attract CD8+ T cells into the tumor are CXCL9, CXCL10, and CXCL11, all of which bind to the chemokine receptor CXCR3 expressed at the surface of CD8+ T cells." (PMID 35439168, 2022). "However, in contrast to its ligands, CXCL9, CXCL10, and CXCL11, the protein expression of the CXCR3 chemokine receptor protein in colon cancer tissue could be associated with increased tumor size, the occurrence of lymph node or distant metastasis, and poor survival." (PMID 36428508, 2022). "We found that the tumor volumes and weights of the MHCC-97H cells + CAFs (CXCL11 + sh-NC) were higher, and those of the MHCC-97H cells + CAFs (NC + sh-LINC00152) group were lower than those of the MHCC-97H cells + CAFs (NC + sh-NC) group." (PMID 36435866, 2022). "The tumor volumes and weights of the MHCC-97H cells + CAFs (CXCL11 + sh-LINC00152) group were similar to those of the MHCC-97H cells + CAFs (NC + sh-NC) group." (PMID 36435866, 2022). "Fourth, despite the impressive promotion in tumor immunity, the roles of the four chemokines-CXCL9, CXCL10, CXCL11, and CCL5-in tumorigenesis and progression were still in debates." (PMID 35692828, 2022). "Specific effects of LINC00152 knockdown or co-effects of LINC00152 and CXCL11 in CAFs on HCC cell phenotypes and tumor growth in mice were examined." (PMID 36435866, 2022). "Oncolytic viruses increase the infiltration and efficacy of CAR-T cells in tumor sites through the production of RANTES, CXCL11, and IL-15." (PMID 36419058, 2022). "Four hub mRNAs in this network, including CXCL10, CXCL11, CCL7, and CCL8, were identified which have also been demonstrated to influence the tumor microenvironment and infection status." (PMID 36544484, 2022). "Despite the intimate crosstalk between the CXCL12- and CXCL11-system, the impact of a combination of CXCL12 and CXCL11 on tumor progression remains vague." (PMID 36539774, 2022). "CXCL9, CXCL10, and CXCL11 bind to CXCR3 and regulate lymphocyte chemotaxis to mediate recruitment of tumor-infiltrating lymphocytes (TIL) for tumor-suppressor activity." (PMID 35269786, 2022). "Following our earlier observations of elevated CXCL11 and CCL20 transcripts in the tumor epithelial compartment, we observed a positive correlation with the expression of their respective receptors, CXCR3 and CCR6, in the microenvironment." (PMID 35394843, 2022). "Some literature suggests that CXCL11 and CXCL10 can promote the proliferation and metastasis of tumor cells." (PMID 35432485, 2022). "IFN-γ also enhances T cell infiltration at the tumour site through the induction of chemokines (CXCL9, CXCL10 and CXCL11)." (PMID 36230780, 2022). "Several lines of evidence currently oppose the possibility that the observed diverse migratory, invasive, and apoptotic responses of the various tumor cells to a combination of CXCL12 and CXCL11 would be due to the differential use of CXCR3A and CXCR3B." (PMID 36539774, 2022). "Among them, Cxcl9, Cxcl10, and Cxcl11 are most related to the recruitment of CD8+ T cells, as CXCR3, the cognate receptor for CXCL9 and CXCL10, is highly expressed in tumor infiltrated CD8+ T cells." (PMID 35145233, 2022). "In 4 out of 5 tumor cell types (A549, A767, DLD-1, MDA-MB-231) CXCL12 and/or CXCL11 induced a slight, but in most cases statistically significant increase in apoptotic cell numbers." (PMID 36539774, 2022). "CXCL9, CXCL10, and CXCL11/CXCR3 axes can induce immune activation and then inhibit tumor growth, which are potential novel therapeutic targets for cancer therapy." (PMID 36090326, 2022). "Within the tumor tissues, the level of LINC00152 decreased in the MHCC-97H + CAFs (NC + sh-LINC00152) / (CXCL11 + sh-LINC00152) groups." (PMID 36435866, 2022).
tumor (continued). "In all tumor cells, levels of pro MMP-9 and pro MMP-2 remained unchanged following treatment with either CXCL12 or CXCL11 alone (100 ng/ml, 24 h) or in combination." (PMID 36539774, 2022). "CXCL9, CXCL10, CXCL11, and CXCR3 recruited and activated immune cells, such as CD8 + T-cells, to suppress tumor progression through CXCL9,-10−11/CXCR3 axis, and they were down-regulated in the high-GATA3 group." (PMID 35647011, 2022). "Nevertheless, although both techniques were demonstrated to be capable of increasing the expression of CXCL-11 in TME, only VV.CXCL11 was able to improve anti-tumor activity after adoptively transferring T cells utilizing mesothelin-redirected CARs." (PMID 35488303, 2022). "Compounds that enhance the expression of CXCL9, CXCL10 or CXCL11 and decrease the expression of CXCR3 on tumor cells have displayed anti-tumor activity." (PMID 35154121, 2022). "To evaluate the correlation between CXCL11 expression and features of the TME, we calculated the tumor purity, stromal scores, immune scores, and ESTIMATE scores across different cancers." (PMID 35935945, 2022). "Compared with CAR/CXCL11, VV.CXCL11 significantly increased intratumoral accumulation of CAR-T cells and potent anti-tumor efficacy was observed, which indicated the therapeutic potential of OVs in assisting CAR T cell therapy." (PMID 33985527, 2021). "In tumor, the expression level of chemokine CXCL9 and CXCL11 was significantly decreased in advanced stage CRC patients (stages IV, n = 11; p = 0.02 and p = 0.045) compared to those in early stages (stages I, II and III, n = 18)." (PMID 34539647, 2021). "Using the median value (50–50 division), the expression level of CXCL9, CXCL10, CXCL11, and CCL5 in tumor or adjacent normal tissues allowed the stratification of patients into groups." (PMID 34539647, 2021). "Strikingly, a large proportion of the IFNγ signature genes were upregulated by SHP2 inhibition specifically in tumor cells in co-culture, including cytokines (CXCL9, CXCL10, CXCL11 and CCL5) and antigen presenting machinery (HLA-A, HLA-B and B2M)." (PMID 33446805, 2021). "CXCL9 and CXCL11 are known for their tumor suppressive properties and are expressed on the DCs; CXCL9 and CXCL11 have been described to enhance antitumor immunity by activating Th1." (PMID 34484333, 2021). "As expected, we also saw CXCL1, CXCL8, CXCL10, CXCL11, CXCL13, and CXCL14 in tumor tissues were upregulated in the results of TCGA data and the difference was statistically significant (p < 0.05)." (PMID 34794429, 2021). "Accordingly, these effector cells are recruited into tumor tissues by the CXCR3 ligands, CXCL9, CXCL10, and CXCL11." (PMID 34885241, 2021). "After data processing, we also found that the expression of CXCL1, CXCL10, CXCL11, CXCL13, and CXCL14 was significantly increased in tumor tissues, and the difference between CXCL10 was the most significant." (PMID 34794429, 2021). "The increased expression of six CXC chemokines (CXCL4, CXCL9, CXCL10, CXCL11, CXCL12, and CXCL13) was related to tumor progression." (PMID 33767987, 2021). "It has been reported that CTCs with higher CXCR3 expression can be recruited to the tumor site by ligands, including CXCL9, CXCL10, and CXCL11, which are known as IFNγ-inducible chemokines." (PMID 34539647, 2021). "IFN-induced STAT1 can subsequently activate chemokines, such as CXCL9, CXCL10, and CXCL11, which can recruit more CD8+ T cells to provide anti-tumor immunity." (PMID 34282238, 2021). "Delivery of CXCL11 to tumor sites significantly increases CAR-T cell infiltration and enhances anti-tumor activity." (PMID 34579759, 2021). "Tumor-infiltrating neutrophils can support adaptive immune responses by recruiting T cells to tumor sites via the secretion of chemokines, such as CCL5, CCL20, CXCL9, CXCL10 and CXCL11." (PMID 34572138, 2021). "The CRC patients were then categorized into two groups according to the expression level of CTTCs (CXCL9, CXCL10, CXCL11, and CCL5) in tumor." (PMID 34539647, 2021).